STIP1 (stress induced phosphoprotein 1)
Diseases named in the same sentence as STIP1 in open-access papers (continued):
Sharing a sentence is not in itself a finding about the gene and the disease.
tumor (continued). "It has been noted that the physical properties of bone matrix, including low oxygen content, acidic pH, plus growth factors, create an environment favorable for tumor growth, and also activate the PrPc transcription to transduce the STIP1 stimulation for osteoclast differentiation." (PMID 28199984, 2017). "Furthermore, co-treatment with the anti-STIP1 neutralizing antibody abrogated these effects, indicating the specific pro-proliferation role of STIP1 in the tumor cells." (PMID 28199984, 2017). "To test whether STIP1 modulates the proliferation of tumor cells, we added human recombinant STIP1 (hrSTIP1) to the culture media." (PMID 28199984, 2017). "To test whether STIP1 histoscores provided information in addition to currently used tumor grading and staging, we analyzed the impact of STIP1 levels on clinical survival only in patients with the same grades or same clinical stages." (PMID 23468915, 2013). "Overall, increased STIP1 expression was observed in the tumour compared to normal tissues." (PMID 19216797, 2009). "Western blot analysis of 5 paired patient ESCC tumor and adjacent normal tissue samples, collected from patients during surgery at the Affiliated Cancer Hospital of Zhengzhou University, further demonstrated increased STIP1 protein expression in the tumor samples." (PMID 41163796, 2025). "Interestingly, recent studies demonstrated STIP1 could be secreted by tumor cells and act as a critical cytokine to regulate malignant phenotype." (PMID 32426271, 2020). "However, recent studies revealed that STIP1 could be secreted by several types of cancer cells, including HCC, and serves as a cytokine in regulating tumor progression, which strongly suggests serum STIP1 is a promising circulating biomarker for HCC." (PMID 32426271, 2020). "Together, these in vitro and in vivo findings demonstrate that STIP1 plays an oncogenic role in promoting ESCC cell proliferation and tumor growth." (PMID 41163796, 2025). "The results demonstrated that STIP1 was highly expressed in ESCC tissues compared to normal tissues, maintained high expression across different tumor stages, and its elevated expression was significantly associated with poor patient prognosis." (PMID 41163796, 2025). "Compared to WT mice, the Stip1‐cKO group exhibited a significant reduction in the number of ESCC tumors and tumor size upon 4NQO treatment." (PMID 41163796, 2025). "STIP1 knockdown or overexpression inhibited or promoted ESCC cell proliferation and tumor growth in vivo." (PMID 41163796, 2025). "The anti‐neoplastic effects of STIP1 inhibitor LCA against ESCC models through inhibition of cell proliferation, induction of apoptosis, and suppression of tumor growth." (PMID 41163796, 2025). "By enhancing the phosphorylation and stability of components within this signaling axis, STIP1 contributes to EMT and subsequent tumor cell migration and invasion." (PMID 41369326, 2025). "Chen et al33 reported that serum STIP1 level was positively correlated with the malignancy degree and tumor size in HCC, indicating STIP1 as a potential biomarker for HCC diagnosis and prognostic evaluation." (PMID 38780206, 2024). "Consistently, a peptide fragment in the DP2 domain of STIP1 (peptide 520) disrupted the interaction between STIP1 and HSP90, thus affecting STAT3 signaling and leading to tumor growth inhibition in vitro and in vivo." (PMID 29914167, 2018). "STIP1 is well studied as HOP, and the heat shock response signaling are extensively involved in tumor genesis and cancer progression." (PMID 28199984, 2017). "Moreover, STIP1 histoscores were significantly higher in high-grade tumors (grade 3) than in low-grade (grade 1–2) malignancies (P<0.0001), suggesting that STIP1 may be a proxy for tumor aggressiveness." (PMID 23468915, 2013).
tumor (continued). "Some proteins from this list have also been identified in tumor studies as clinical outcome predictors (NOV, CLU TNC, POSTN, IGFBP2, LCN2) or mediators of resistance to chemotherapy (CLU, FBLN1, THBS, STIP1, PTGES3, IGFBP4, ATOX1)." (PMID 19936259, 2009). "LCA can inhibit the STIP1/AHCY/LDHA axis and inhibit tumor development mediated by the gly." (PMID 41163796, 2025). "Using IHC and IF assays, we evaluated the expression of GOLPH3 and STIP1 in six paired tumor and adjacent non-cancerous tissue specimens from patients with PDAC." (PMID 33134174, 2020). "Moreover, we found the predictive performance of STIP1 was stronger than other biomarkers such as AFP, tumor size, and tumor number." (PMID 32426271, 2020). "The results also showed that the expression levels of GOLPH3 and STIP1 were higher in tumor tissues than in adjacent non-cancerous tissues." (PMID 33134174, 2020). "Further investigation demonstrated pretreatment STIP1 level was an independent indicator for both tumor progression and survival, regardless of therapeutic approach." (PMID 32426271, 2020). "In addition, our results further indicated that GOLPH3 expression correlated positively with STIP1 expression in PDAC tissues, and their co-localization in tumor cells implied their interaction." (PMID 33134174, 2020). "In addition, a more in-depth investigation is needed to screen small molecules as anti-tumor drugs to inhibit the intracellular interaction of GOLPH3 and STIP1 in PDAC." (PMID 33134174, 2020). "We found that the STIP1 level was increased in tumor tissue (T) compared with that in adjacent non-cancerous tissue (ANT), and correlated positively with the GOLPH3 level." (PMID 33134174, 2020). "Thus, the tumor STIP1-ALK2 signaling and osteoclast STIP1-PrPc signaling aggravate the vicious cycle in osteolytic bone metastasis from RCC." (PMID 28199984, 2017).
cancer (37 papers, 2012 to 2025). A tumor composed of atypical neoplastic, often pleomorphic cells that invade other tissues. "Stress-Inducible Protein-1 (STIP1) is a co-chaperone that associates directly with heat shock proteins, and regulates motility of various types of cancer." (PMID 29335007, 2018). "STIP1 is located at 11q13, and copy number gain of this region has been found in cancers and linked to poor prognosis." (PMID 29335007, 2018). "The STIP1 gene is located at 11q13, and copy number gain of this region has often been shown in cancers and is linked to poor prognosis." (PMID 28199984, 2017). "These unbiased proteomic data provide additional evidence that LCA alters cancer cell metabolism through direct binding to STIP1." (PMID 41163796, 2025). "Using proximity proteomics, researchers confirmed a tight interconnection between DNAJ-PKA, BAG2, and Stip1 in carcinoma cells." (PMID 41369326, 2025). "The impact of STIP1 in different types of cancers and the pathways activated by its overexpression were extensively revised in a recent study." (PMID 36713524, 2022). "We have previously shown that STIP1 stabilizes the protein tyrosine kinase JAK2 in cancer cells via HSP90 binding." (PMID 35269562, 2022). "STIP1 has also been suggested to be used as a prognostic biomarker for cancer treatment based on its high expression significantly associated with shorter OS." (PMID 36277962, 2022). "Supported by the results with other cancers, our data suggest that STIP1 overexpression is an independent prognostic marker associated with OSCC patient outcome." (PMID 36713524, 2022). "In this study, we explored the influence of the stress induced phosphoprotein 1 (STIP1), which is frequently reported to be highly expressed in many cancers, in OSCCs." (PMID 36713524, 2022). "Collectively, these results indicate that JAK2-mediated phosphorylation of STIP-1 is critical for sustaining the JAK2/STAT3 signaling pathway in cancer cells." (PMID 35269562, 2022). "STIP1 and HSP90AB1 are found associated with cell metastasis, apoptosis and other oncogenic functions in human cancer cells." (PMID 32194784, 2020). "Although LSD1 protein levels were decreased in STIP1-silenced cancer cells, the proteasome inhibitor MG132 restored its normal expression." (PMID 29593255, 2018). "STIP1 has been reported to be up-regulated in various types of cancer, including hepatocellular carcinoma, pancreatic cancer, ovarian cancer, colon cancer, and cholangiocellular carcimoma." (PMID 29335007, 2018). "Increased STIP1 expression is involved in the pathogenesis of gynecologic malignancies, including ovarian and endometrial cancer." (PMID 29304094, 2018). "The knockdown of STIP1 expression in cancer cells has been shown to reduce tumor invasiveness through downregulation of matrix metalloproteinases (MMPs)." (PMID 29304094, 2018). "Although high expression of STIP1 has been reported in various cancers, STIP1 signal transduction is much less studied." (PMID 28199984, 2017). "We conclude that STIP1 overexpression in cancer cells is involved in the regulation of the JAK2-STAT3 pathway." (PMID 27409672, 2016). "In cancer cells, knockdown of STIP1 expression has been shown to reduce tumor invasiveness through the downregulation of matrix metalloproteinase-2 and RhoC GTPase and related inhibition of pseudopodia formation." (PMID 27409672, 2016). "Repression of STIP1 or interruption of the STIP1-HSP90 interaction warrant further scrutiny as potential strategies for cancer treatment." (PMID 27409672, 2016). "The expression of STIP1 in various types of cancer suggests that this molecule has an anti-apoptotic role and/or promotes cancer cell survival." (PMID 23468915, 2013). "The majority of grade 3 tumors showed a STIP1 histoscore >169; in particular, 92.8% (77/83) of the serous type, 92.3% (12/13) of endometrioid, and 76.5% (13/17) of the mixed type carcinomas showed a high STIP1 expression." (PMID 23468915, 2013).
cancer (continued). "Among genes downregulated by clofibrate, the major part belonged mainly to functional groups: “cancer” (STIP1, HNRNPA1, VIL1, and CDH1) and “cellular assembly and organization” (CLASP1 and MACF1)." (PMID 22619672, 2012). "STIP1 knockdown inhibited cancer cell growth in vitro and in vivo." (PMID 41163796, 2025). "STIP1 has been identified as a key player in cancer development and metastasis." (PMID 38780206, 2024). "The strategy of reducing STIP1 levels has been successfully applied in several cancer cell lines." (PMID 36713524, 2022). "Notably, the subcellular localization of GOLPH3 and STIP1 was observed to be mainly in the cytoplasm of the cancer cells." (PMID 33134174, 2020). "In addition, GOLPH3 and STIP1 protein levels were dramatically upregulated in PDAC tissues compared with those in their matched para-cancer counterparts." (PMID 33134174, 2020). "STIP1 represents an attractive potential target for cancer treatment." (PMID 28199984, 2017). "STIP1 has been reported to be up-regulated in various types of cancer." (PMID 28199984, 2017). "Here, we used antibody transfection experiments with three STIP1 monoclonal antibodies (M02, M04, and M06) to investigate whether endogenous STIP1 is involved in cancer cell survival." (PMID 27409672, 2016). "The amount of JAK2 protein increased in STIP1-knocked-down cancer cells after exposure to MG132." (PMID 27409672, 2016). "STIP1 represents an attractive candidate for cancer therapy." (PMID 23468915, 2013). "The high expression of STIP1 increased the interaction between AHCY and LDHA and then AHCY recruits PRMT3 to methylate LDHA at R106 to promote the proliferation of cancer cells." (PMID 41163796, 2025). "In summary, STIP1 acts through AHCY in a moonlighting capacity to post‐translationally activate LDHA and reprogram cancer cell metabolism, fueling ESCC progression." (PMID 41163796, 2025). "STIP1, called heat shock protein–organizing protein, is reportedly overexpressed in HCC and accelerates cancer-cell growth and migration by interacting with Axin to activate β-catenin/TCF signaling." (PMID 40636922, 2023). "Here, we further examined the reciprocal interactions between STIP1 and JAK2 with the goal of advancing our understanding of their functional role in cancer cells." (PMID 35269562, 2022). "This is, to our knowledge, the first study to demonstrate that tyrosine phosphorylation of STIP1, mediated by JAK2, can affect a number of biological functions in cancer cells." (PMID 35269562, 2022). "As a crucial co-chaperone of HSP90 complex, STIP1 was reported to execute its elemental function with HSP90, resulting in rapid cancer progression." (PMID 32426271, 2020). "Based on the Oncomine database, we found that mRNA expressions of TCP1, CCT2, CCT6A, CCT7, STIP1 and HSP90AB1 were significantly upregulated in cancerous samples compared with normal samples in various types of cancer, including BC." (PMID 32194784, 2020). "In this respect, the activity of Hsp90 in cancer cells is highly dependent on other chaperones and co-chaperones like AHA1, p23, HOP (also known as STIP1), CHIP (STUB1), Cdc37, Hsp40 and Hsp70." (PMID 30138434, 2018). "Repression of STIP1 expression through siRNA blocked MMP-9 expression and activity in various cancer cells." (PMID 29304094, 2018). "Moreover, increased expression of STIP1 may indicate poor survival outcome in cancer patients." (PMID 28852266, 2017). "Recent evidence indicates that small compounds or peptides that interfere with the interaction between the TPR2A domain of STIP1 and the MEEVD motif of HSP90 can display anti-cancer activity both in vitro and in vivo." (PMID 27409672, 2016). "Other genes down-regulated by rosiglitazone belonged mainly to two functional groups: “cancer” (RPS27A, SORBS2, STIP1, FGA, FGFR2, SSH3, EPN1) and cell death (SORBS2, STIP1, GAS2, EPN1)." (PMID 22761953, 2012). "The downregulated genes belonged mainly to the “cancer” biofunction (RPS27A, HNRNPA1, STIP1, and TFDP1)." (PMID 22619672, 2012).
cancer (continued). "This STIP1‐mediated methylation and activation of LDHA by the AHCY‐PRMT3 complex leads to heightened glycolytic flux, meeting the bioenergetic and biosynthetic demands of rapid cancer cell proliferation." (PMID 41163796, 2025). "The protein folding activity of chaperones is hyperactive in cancers due to enhanced interactions of phosphorylated Hsp90 with Hsp70/Hsp90-organising protein (HOP, also known as STIP1) and reduced interaction with C-terminal Hsp70 interacting protein (CHIP, also known as STUB1)." (PMID 30917858, 2019). "Finally, the immunohistochemical expression of STIP1 and LSD1 showed a positively correlation in human cancer specimens." (PMID 29593255, 2018).
neurodegenerative disease (5 papers, 2017 to 2025). A disorder of the central nervous system characterized by gradual and progressive loss of neural tissue and neurologic function. "For the purpose of this review, we will focus mainly on the roles of Hsp70 and Hsp90 as well as of the critical co-chaperone stress-inducible phosphoprotein I (STI1, STIP1) and their regulation of protein misfolding and signaling in neurodegenerative diseases." (PMID 28559789, 2017).
neurodevelopmental disorder (1 paper, 2023). A behavioral and cognitive disorder with onset during the developmental period that involves impaired or aberrant development of intellectual, motor, or social functions. "Since ASD is a neurodevelopmental disorder and several MAR-ASD aAb targets, namely STIP1 and CRMP-family proteins, are upregulated during processes such as neural progenitor cell induction, we examined Ab deposition in the brains of exposed offspring." (PMID 36973347, 2023).
neurological disorders (1 paper, 2022). "The autoimmune response against the extracellular function of STIP1 in the PrPC-mediated signalling pathways and the chaperone machinery may therefore predispose individuals to neurological diseases beyond Parkinson’s disease." (PMID 35626686, 2022). "Given STIP1’s role in brain development and its neuroprotective role in neurological disorders, we posit that the presence of autoantibodies against the STIP1 protein may contribute to Parkinson’s disease pathogenesis, predisposing individuals to Parkinson’s disease development." (PMID 35626686, 2022).
STIP1 also shares sentences with these, for which no sentence is quoted: infection (6 papers); tauopathy (3); melanoma (2); prion disease (2); protein misfolding diseases (2); renal cell carcinoma (2); adenocarcinoma (1); African sleeping sickness (1); Anxiety (1); astrocytic tumor (1); astrocytoma (1); bacterial infection (1); blast (1); Brain atrophy (1); cerebral infarction (1); Cerebral ischemia (1); cervical carcinoma (1); Chagas disease (1); cholangiocellular carcinoma (1); chronic hepatitis B (1); co-infection (1); Cognitive impairment (1); colorectal (1); endometrioid carcinomas (1); Fever (1); heart failure (1); hyperglycaemia (1); Infertility (1); kidney failure (1); leishmaniasis (1).
A further 11 diseases each share a sentence with STIP1 in 1 paper.